MYC (MYC proto-oncogene, bHLH transcription factor)
Diseases named in the same sentence as MYC in open-access papers (continued):
Sharing a sentence is not in itself a finding about the gene and the disease.
breast cancer (continued). "Interestingly, MYC depletion or inhibition by MYCi975 also increased the expression of YAP and TAZ targets in H1299, H1975 and H358 cells consistent with previous reports in liver and breast cancer models." (PMID 39455556, 2024). "Further investigation of ESR1 mutant in a clinical breast cancer cohort (SCAN-B31; n cases = 27; n controls = 108, see Methods for details) largely confirmed our cell model results (top enriched pathways: E2F targets, G2M checkpoint, MYC targets, and mTORC1 signaling)." (PMID 38519482, 2024). "The downstream targets of YTHDF1 may be related to MYC signaling regulation and T-cell differentiation, and YTHDF1 amplification resulted in reduced immune cell infiltration and significantly worse clinical features in breast cancer patients." (PMID 38339157, 2024). "However, TRPS1 is often co-amplified along with the rest of the chromosomal segment 8q23–q24, where the proto-oncogene MYC resides, making it difficult to discern whether TRPS1 amplification is a driver of breast cancer progression." (PMID 38377146, 2024). "This association was mediated through miR-155 inhibiting the upstream inhibitor of c-MYC, FOXO3a, thereby initiating activation of c-MYC (PIK3R1-PDK/AKT-FOXO3a-cMYC pathway) and highlighting the pivotal role of miR-155 in regulating glucose metabolism in breast cancer." (PMID 38538285, 2024). "Similarly, in a MYC knockdown experiment in medulloblastoma (GSE22139) and in an induced Myc expression experiment in MCF-7 breast cancer cells (GSE11791), MYC ranked first and second in the confidence levels and was correctly predicted by 6 or 5 out of 6 tools respectively." (PMID 38032891, 2023). "Interestingly, in cervical cancer, unlike in breast cancer, the tumor-promoting effect of circAMOTL1 was independent of c-MYC regulation, probably because circRNA was not translocated into the nucleus." (PMID 36768425, 2023). "Besides, c-MYC mRNA was significantly upregulated in macrophages after CSF-1 stimulation, boosting macrophage proliferation.Via JAK1/STAT3 signaling pathway, IL-11 induces c-MYC expression to promote breast cancer bone metastasis." (PMID 36721232, 2023). "The exosomal miR-105 secreted by breast cancer (BC) targets MXI1, activates the MYC pathway in CAFs, enhances the glycolysis and glutamine decomposition of CAFs, and detoxifies the metabolites (lactate and NH4 +) to fuel adjacent cancer cells." (PMID 36899389, 2023). "MYC dysregulation appeared to be tissue-specific tissue during tumorigenesis; MYCN was described to be aberrantly expressed in neuronal or neuroendocrine tumors, and more recently, in ovarian cancer, prostate cancer, and in a subset of breast cancer with poor prognosis." (PMID 36983070, 2023). "This might be dependent on the c-MYC mediated crosstalk between TME and breast cancer cells." (PMID 36721232, 2023). "Furthermore, we deciphered its transcriptional regulatory program and report that ABCA1 expression is low in epithelial, non-metastatic breast cancer cells via MYC-mediated repression of an E-box element in its proximal promoter." (PMID 35327383, 2022). "Interestingly, a previous study found that MYC promoter interactions with enhancers in the PVT1 locus could be enhanced by a distinct mechanism, inactivation of the PVT1 promoter, in breast cancer cells." (PMID 34911936, 2021).
breast cancer (continued). "Furthermore, we sorted the basal breast cancer patients from low to high according to their mRNAsi values and found that patients with high mRNAsi are usually accompanied by high expression of tumor stem-related genes such as KDM5B, BMI1, MYC, and EZH2." (PMID 34646403, 2021). "Conversely, SOX2 or MYC mRNAs were significantly downregulated in cells expressing TrkA-K538N, nearly to the levels found in the vector controls, suggesting that TrkA kinase activity is essential for inducing STAT3 target gene transcription in breast cancer cells." (PMID 34066153, 2021). "Given the mechanism that ACTL6A activated the MYC/ CDK2 axis, we hypothesized that a CDK2 inhibitor would have potentially therapeutic effects against TNBC in combination with the first-line chemotherapy drug of breast cancer, paclitaxel (PTX)." (PMID 33541412, 2021). "However, ADHFE1 has been reported to form a mutual regulatory loop with MYC, and ADHFE1 may play an oncogenic role in breast cancer via inducing metabolic reprogramming." (PMID 34179501, 2021). "Also, no mutations were detected for other described breast cancer‐associated genes (e.g., RAD51, RAD50, p27, ESR1/2, ERBB2, ERBB3, AKT1, CCDN1, FGFR1, MYC, and RB1) in any of the tissues or the CTC cell line." (PMID 32667137, 2020). "Likewise, in chromosome 8, arm-level gains of 8q and losses of 8p in human breast cancer SCNAs were further segmented into three amplification peaks involving STK3, MYC, and PTK2 and three deletion peaks involving CSMD1, PSD3, and IDO1 in hg19-aligned CMT SCNAs, respectively." (PMID 32680987, 2020). "Among the recurrently amplified and deleted loci, we noted that canonical oncogenes, such as EGFR and HRAS, were recurrently amplified in CMTs; however, amplification of ERBB2 and MYC, which is common in human breast cancers, was not reflected in the GISTIC peaks of CMTs." (PMID 32680987, 2020). "Importantly, MYC is amplified in 53% of basal-like breast cancers, which are triple-negative breast cancer (TNBC) lacking the expression of estrogen receptor, progesterone receptor and HER2." (PMID 30076412, 2019). "In addition to MYC, TSPX also represses MYB, an oncogenic transcription activator involved in the development of various malignant tumors including leukemia, colon cancer, and breast cancer, as well as prostate cancer." (PMID 30863497, 2019). "To determine whether primary breast cancer could be targeted by a therapeutic strategy that reactivates MYC’s apoptotic potential via BH3 mimetics, we assessed the expression of MYC, BCL-2, BCL-XL, and MCL-1 using a tissue microarray (TMA) of 231 primary breast cancer samples." (PMID 30728358, 2019). "Altogether, these results suggested that expressions of both MYC and CD47 were positively regulated by MALAT1 in triple negative and Her-2 positive breast cancers, which implied that MALAT1 might get involved in immune escape of breast cancer cells." (PMID 29416769, 2018). "Through analysis using the METABRIC and TCGA datasets, we provide evidence that MYC and FAM84B are frequently co-amplified in breast cancer, but in contrast with MYC, FAM84B is frequently overexpressed in the luminal subtype, whereas MYC activity affect basal breast cancer outcomes." (PMID 30526553, 2018). "In addition, we found that the RNAi‐mediated downregulation of MYC reduced the growth suppressive effect of T‐025 in MYC‐amplified SK‐BR3 or MCF7 breast cancer cell lines, whereas the depletion of DYRK1A did not reduce the effect of T‐025." (PMID 29769258, 2018). "For instance, MYC addicted TNBCs cells have been shown to impart a specific dependency on the spliceosome via BUD31 and SF3B1 and impaired tumourigenesis was observed when SF3B1 was knocked down or pharmacologically inhibited in breast cancer cells MYC hyperactivation." (PMID 29848666, 2018).
breast cancer (continued). "Further, although only amplified MYC did not significantly worsen the prognosis in breast cancer patients categorized as ER‐positive, HER2‐negative, and high‐proliferative subtype, patients with both high‐expressed CLK2 and MYC amplification showed significantly poor outcomes." (PMID 29769258, 2018). "Although a previous report has evaluated the associations between 8q24 region amplification and CCAT2 expression in breast cancer patients, to our knowledge, there is no data regarding the association between CCAT2 expression and precise MYC copy number, which should be evaluated in future studies." (PMID 28480695, 2017). "Firstly, it indicates that MYC overexpression is associated with poor DFS/RFS and OS, that demonstrates that MYC may be a potential therapeutic target of breast cancer, especially in phenotype of negative hormone receptors." (PMID 29212204, 2017). "One explanation for this hTERT down-regulation, which could account for growth inhibition in the breast cancer cells, could be due to a decrease in the downstream target of SIRT1, FOXO3a and c-MYC, which has been shown to increase hTERT expression in a SIRT1-dependent manner." (PMID 26459286, 2015). "Furthermore, more radiogenic breast cancers (7 of 9, 77%) than sporadic breast cancers (4 of 20, 20%) had a c-MYC to centromere 8 ratio >1.10 (Fisher's exact test, P=0.010), indicating that locus-specific c-MYC copy number gain is more common in radiogenic breast cancer." (PMID 25531321, 2015). "Since the GDS3283 is a breast cancer data set, we selected the ChIP-seq experiments from breast cancer cell lines (T47D and MCF7 cells) to generate the regulatory TF network with Q < 0.001, which contained five significant TFs: ESR1, GATA3, FOXA1, MYC and E2F1." (PMID 24302579, 2014). "We have therefore identified a novel estrogen/MYC/miR-26 axis that mediated estrogen stimulated cell growth via CHD1, GREB1 and KPNA2 and suggest that upregulation of miR-26a and miR-26b may be considered as novel strategy for breast cancer therapy." (PMID 24735615, 2014). "It has been reported that MYC and BCL2 act synergistically to promote primary cells into tumour cells, while in our work, MYC is dependent on BCL2 to influence the outcome of breast cancer (with p-value of 0.0119) and BCL2 also relies on MYC significantly (with p-value of 0.0388)." (PMID 24637666, 2014). "Thus, MYC directly controls the UPR and autophagy to control cell fate in ER + breast cancer cells under specific cellular signals that may be initiated by changes in intracellular glucose or glutamine." (PMID 25339305, 2014). "Our analysis of a breast cancer dataset finds that the positive feedback loops across 7 genes, AR, ESR1, MYC, E2F2, PGR, BCL2 and CCND1 are conserved across the basal/triple negative subtypes in multiple datasets that could potentially explain the aggressive nature of this cancer subtype." (PMID 23368093, 2013). "However, although a loop between the SNP and the MYC promoter was identified in MCF7 breast cancer cells, this loop is not anchored by either ERα or Pol II, suggesting it does not mediate MYC transcription in this cell line." (PMID 23145106, 2012). "We used quantitative RT-PCR to confirm that the transgenic mice used in these experiments have little to no expression of the c-MYC mRNA transcript in the peripheral blood cells relative to the high levels observed in the mammary tumors from the transgenic mice." (PMID 21781289, 2011). "We also quantified the level of MYC in the same breast cancer samples to investigate whether or not a high level of MYC expression could be responsible for the observed NDRG2 down-regulation." (PMID 21226903, 2011).
breast cancer (continued). "To evaluate the functional significance of the predicted shared MYC/KLF6 transcriptional targets, we examined expression data derived from a model of MYC-driven cellular transformation of quiescent human mammary epithelial cells and from MMTV-Myc-driven mammary tumors in mice." (PMID 18190704, 2008). "Therefore, activating mutations of K-ras were not a common occurrence and was not an explanation for MYC independence in our lung model, in contrast to what has been previously reported for breast cancer." (PMID 18461184, 2008). "Hence, directly inhibiting c-MYC to reverse tamoxifen resistance in breast cancer is not feasible." (PMID 35267559, 2022). "Therefore, we speculated that CLDN6 may affect c–MYC by interacting with TAZ, and the mechanism by which CLDN6/TAZ/c–MYC mediated signaling controls glycolysis and proliferation in breast cancer has not been investigated to our knowledge." (PMID 35008557, 2021). "However, even breast cancers that are not MYC-driven appear to rely on intact AAR pathways to drive adaptive cancer cell survival; for example, leucine deprivation in glutamine-independent luminal breast cancer cells inhibits growth via GCN2-mediated signalling." (PMID 29940911, 2018). "Interestingly, there was no statistical significance of high MYC expression in TNBC and HER-2 status groups, that further showed MYC overexpression could be a target for breast cancer of negative hormone receptors." (PMID 29212204, 2017). "Similarly, we expanded the breast cancer input layer with the hyaluronan-mediated motility receptor (HMMR) connected to FN1; the TGFBR connected to SNAI1 and SNAI2; the interLeukin 1 receptor type I (IL1R1) and the thyroid hormone receptor beta (THRB) connected to TRAF1 and MYC, respectively." (PMID 28775339, 2017). "Furthermore, a mechanism has been identified that could be responsible for increased c-MYC expression in radiogenic breast cancer without the requirement of c-MYC amplification." (PMID 25531321, 2015). "However, we could not find any clear correlation between SQLE and MYC expression, suggesting that the poor outcome typical of breast cancer patients with high SQLE does not simply reflect MYC activation." (PMID 26610607, 2015). "Clinical genomic data demonstrated that the percentages of MYC amplification and mRNA were upregulated approximately two-fold higher in the TNBC patients than the non-TNBC breast cancer patients." (PMID 40282497, 2025). "In ERα-negative breast cancer cells, CAF-secreted IL-6 decreases c-MYC expression and suppresses tumor growth." (PMID 36721232, 2023). "Although stemness and EMT markers, such as SOX2, c-MYC, and NANOG, were downregulated in several YTHDC2-knocked-down breast cancer cells, a common target gene of YTHDC2 in breast cancer cells was not identified." (PMID 36245989, 2022). "The amplification of PTK2, MYC, NBN, and RAD21 found prognostic biomarkers independent of breast cancer subtype." (PMID 35494043, 2022). "Although the mRNA expression of stemness markers, such as SOX2, c-MYC, and NANOG, was reduced by YTHDC2 knockdown, the alteration of gene expression pattern was not the same for all of breast cancer cell lines." (PMID 36245989, 2022). "Breast cancer cell lines we used in this study include MCF7, MDAMB231, MDAMB361 and HCC1937, which are all not MYC-driven as compared with the quasi-normal cell line MCF10A." (PMID 33879154, 2021).
breast cancer (continued). "For example, in a breast cancer model, gain of both PVT1 and MYC resulted in an increased proliferation of cells which was not evident by increase in PVT1 and MYC alone." (PMID 33499210, 2021). "Similar to pancreatic cancer cells that express c-MYC or mutant KRAS in a ligand-controlled manner, the survival of KRASG12D-expressing mammary tumor cells that are being maintained in culture did not rely on the oncogenic driver." (PMID 34145248, 2021). "This priority list includes established breast cancer driver genes such as MYC and GATA3 but also includes many genes with no reported role in breast cancer." (PMID 31910858, 2020). "TLK2 amplification is independent of most known amplified oncogenes in breast cancer (that is, HER2, CCND1 and MYC), except RPSKB1." (PMID 27694828, 2016). "Genes with recurrent amplifications in breast cancer showed 100% (ERBB2, FGFR1), 96% (CCND1), and 88% (MYC) concordance for the amplified/non-amplified status." (PMID 27028851, 2016). "This suggests that TLK2 is frequently co-amplified with RPS6KB1, but not with other known amplified genes in breast cancer such as ERBB2, MYC, CCND1, and so on." (PMID 27694828, 2016). "We also demonstrate that the frequency and magnitude of c-MYC amplification and c-MYC protein expression is significantly higher in breast cancer with antecedent radiation exposure compared with breast cancer without a radiation aetiology." (PMID 25531321, 2015). "In sum, the loss of HDAC1 and HDAC2 increases C3 and NCOA2, but not CLU, ERBB2, MYC, or PGR, providing evidence that C3 and NCOA2 are repressed in breast cancer cells by the HDAC1/2 components of the Sin3A repressive complex." (PMID 20920219, 2010). "Additionally, in ER+ breast cancer cells, EZH2 has been found to noncanonically interact with estrogen receptor α (ERα) and β-catenin, forming a ternary complex that binds to MYC promoter at the LEF/TCF-binding sites, thereby inducing its transcription." (PMID 37175580, 2023). "When focusing on ER+ breast cancer only (30 ER+/HER2− [human epidermal growth factor receptor 2], 1 ER+/HER2 unknown), we also observed a trend toward MYC amplification enrichment in non-responding patients." (PMID 37642941, 2023). "Similarly, activities of E2F and MYC are highly positively correlated in both TCGA and METABRIC breast cancer patient samples irrespective of their subtype (Spearman correlation coefficient r=0.82, both in TCGA and METABRIC datasets)." (PMID 35655310, 2022). "Next, an in silico analysis showed that genes related to breast cancer, including HES1, MYC, CCND1, FOS and PGR, could be regulated by NRIP1 (data not shown)." (PMID 34707101, 2021). "However, PIAS1 is essential for viability of MYC-dependent breast cancer cells, as the silencing of PIAS1 reduces the proliferation of MYC-dependent MDA-MB-231 cells, but not MYC-independent MCF7 cells." (PMID 34503213, 2021). "MITF-directed RNAi did not affect c-MYC mRNA expression in MITF-negative melanoma (A375) and non-melanocytic tumor cells (MCF7 breast cancer and U2OS osteosarcoma cells) in contrast to MITF-dependent 501 mel cells ruling out siRNA-mediated off-target effects on c-MYC." (PMID 30651597, 2019). "Importantly, this effect is restricted to cells where MYC forms chromatin loops with PVT1, for example, breast cancer, as opposed to colorectal cancer or cervical carcinoma cells where MYC loops to the CCAT1 enhancer." (PMID 30451365, 2019). "Analysis of publically available Molecular Taxonomy of Breast Cancer International Consortium (METABRIC) and TCGA data implies that FAM84B has effects on breast cancer that may be independent of MYC." (PMID 30526553, 2018).